IL2 (interleukin 2)
Diseases named in the same sentence as IL2 in open-access papers (continued):
Sharing a sentence is not in itself a finding about the gene and the disease.
tumor (continued). "Preclinical mouse models have showed that combined administration of a fusion protein, consisting of a Fc domain and integrin targeting peptide, with albumin/IL-2 or anti-PD-1 immunotherapy was able to significantly enhance anti-tumor immunity and improve survival." (PMID 32752094, 2020). "IL2 plays a critical role in immune system activation that could provide a useful way to stimulate anti-tumor immune response." (PMID 32560387, 2020). "A pre-clinical study, focusing on human mammary gland carcinoma, showed that treatment with adoptive transfer of BrHPP + IL-2-expanded Vγ9Vδ2 T cells alone had a slight impact on tumor growth; however, when combined with trastuzumab (anti-Her2 Ab), the outcome was significantly improved." (PMID 32456316, 2020). "It is interesting to note that while KRAS and EMT pathways that result in aggressive tumor biology are enriched in the GR-high group, immune pathways IL2 and apoptosis are also enriched, which may play a role in influencing overall survival." (PMID 32629782, 2020). "Similarly, IL-15 in combination with IL-2, boosted the proliferation as well as the in vitro anti-tumor activity of ZOL-expanded Vγ9Vδ2 T cells." (PMID 32456316, 2020). "Among the proposals advanced to explain the effect are enhanced levels of monocyte chemoattract protein-1 (MCP-1); elimination of sinks for homeostatic cytokines, such as interleukin-2 (IL-2), IL-7, and IL-15; and downregulation of indoleamine 2,3-dioxygenase in tumor cells." (PMID 32707894, 2020). "Moreover, IL-2 stimulates suppressor-type immune cells, which in turn curtail anti-tumor effector cells." (PMID 33353953, 2020). "The TILs were then stimulated with the PanTT26 tumour cell line (autologous) three times to see whether repeated exposure of the IL-2/IL-15/IL-21-conditioned TILs to the tumour would lead to enrichment of tumour epitope-reactive T cells." (PMID 30377343, 2019). "NK cells are lymphocytes of the innate immune system that control pathogens and tumor cells by limiting their spread and subsequent tissue damage under the stimulation of the endogenous interleukin-2 (IL-2) and interleukin-12 (IL-12), in addition to immune cell activation and cytokine production." (PMID 31736966, 2019). "Furthermore, the IL-2-antibody complex promoted antitumor immunity in mice by activating tumor-reactive CD8+ T cells." (PMID 31114758, 2019). "However, multiple pathways have been proposed, such that undifferentiated T cells would possess greater proliferative potential, retain the ability to produce IL-2, and display greater anti-tumor efficacy." (PMID 30886618, 2019). "Presumably, combination of TKD/IL-2-stimulated NK cells with several therapeutic antibodies could improve the anti-tumor activity of the adoptive cell immunotherapies." (PMID 30967859, 2019). "Whereas cHsp70 contributes to tumor cell survival via multiple anti-apoptotic functions, extracellular Hsp70 in combination with pro-inflammatory cytokines such as interleukin-2 (IL-2) can elicit an anti-tumor immune response mediated by natural killer (NK) cells." (PMID 31430337, 2019). "They demonstrated that these CAR T cells could secrete IL-2 and lyse tumor cells in an antigen-specific manner." (PMID 30842774, 2019). "IL-6 and IL-2 levels appear to correlate with the BC patient outcome and could be considered in combination as putative tumor biomarkers as well as a prognostic marker for RT-induced toxicity (i.e., erythema and fatigue)." (PMID 30658426, 2019). "Whether IL-2 participates in the resistance of tumour cells by inducing G1 arrest to enable cells to activate DNA repair to increase its survival capacity remains to be addressed in further studies." (PMID 31662754, 2019). "Given its impressive effect on enhancing tumor-specific T cell responses, sum-IL-2 may induce the expression of PD-L1 on a tumor cell and/or APCs42." (PMID 31462678, 2019).
tumor (continued). "Once activated, the ILC3s secret IL-2, which stimulates expansion of tumor-specific lymphocytes; however, since ILC3s also provide an innate source of IL-22 which might favor tumor growth, their role in NSCLC still remains to be identified." (PMID 32039025, 2019). "This alludes to the possibility that IL-2 could be a right candidate cytokine for T cell activation and tumor killing." (PMID 31462678, 2019). "Therefore, it is logical to combine both IL-2 and PD-1 blockade to synergize their effect on immune responses for tumor control, especially during TKI treatment." (PMID 31462678, 2019). "Similarly, all but the FR-negative HOS-143b tumor cells triggered high levels of IFNγ, IL-2, and TNFα production after 44 h of co-culture at an E/T ratio of 1:1 with E2-CAR-T cells." (PMID 30941303, 2019). "There are many tumour-CAF co-targeting clinical trials currently recruiting patients: for example, RO6874281 is a recombinant fusion protein that targets an engineered, variant form of IL-2 to human FAP+ cells, to stimulate a local immune response and therefore improve anti-tumour immunity." (PMID 31289350, 2019). "However, maintaining γδ T cell activation by IL-2 supplementation would only be beneficial if we can overcome the obstacle to obtain persistent anti-tumor Vγ9Vδ2 T cell populations." (PMID 31475003, 2019). "CD8+ Tcells effect tumor killing in two ways; (i) through the secretion of cytotoxic molecules (granzyme B and perforin) and, (ii) through the secretion of proinflammatory cytokines (IL-2, TNF-α, and IFN-g)." (PMID 30979375, 2019). "This likely reflected a cascade of proTα-induced effects that relates to: (i) TNF-α production by peritoneal macrophages, (ii) enhancement of antitumor NK cell cytotoxicity, and (iii) generation of MHC-restricted tumor-specific CD8+ cytotoxic T-cell responses in an IL-2-dependent manner." (PMID 31717548, 2019). "Therefore, TGF-β-dependent fine-tuning of 4-1BB signaling contributes to “regulatory” CD73+CD8+ T cell responses via two different aspects: (i) the signal intensity of the STAT3 pathway and (ii) the levels of IFN-γ and IL-2 production in the tumor." (PMID 30635578, 2019). "Similarly to IL-2, there have been various analogs of IL-15 developed to increase the anti-tumor efficacy and lower the toxicity." (PMID 31179236, 2019). "In addition, CD4+ T cells also orchestrated dendritic cells (DCs) to activate CD8+ T cells either by cross-presenting tumor antigens to CD8+ T cells or by inducing the production of IL-2." (PMID 30913212, 2019). "Combining T cell growth factor IL-2 with the TIL infusion product resulted in a greater therapeutic potency of TIL compared to lymphokine-activated killer (LAK) cells produced from peripheral blood lymphocytes in the presence of IL-2 in mice with metastases from various tumor types." (PMID 30470934, 2019). "Similarly, TNC-targeting antibodies have also been conjugated with IL-2, and have shown some preliminary signs of anti-tumor activity in advanced solid tumors and metastatic breast cancer." (PMID 31106200, 2019). "These exhausted CD8+ T cells express co-inhibitory molecules (e.g., PD-1, LAG-3, TIM-3, TIGIT) and lose the ability to produce multiple cytokines such as interferon (IFN)-γ, tumor necrosis factor (TNF)-α, and interleukin (IL)-2, namely they lose anti-tumor activities." (PMID 30696484, 2019). "Addition of cyclophosphamide to TIL and IL-2 further potentiated the anti-tumor effect of TIL." (PMID 30470934, 2019). "Other indications of the functional role of CD56 in the immune system include: the CD56-mediated inhibition of tumor cell growth by IL-2-activated NK cells, the induction of NK cell maturation by CD56 forming a developmental synapse, and the role of CD56 as a pathogen recognition receptor." (PMID 31336622, 2019). "A tumor cell to T cell ratio of 16:1 showed a significant reduction of both IL-2 and IFN-γ levels." (PMID 30699956, 2019).
tumor (continued). "Furthermore, in a study using syngeneic BALB/c and nude mice, exosomes derived from TS/A or 4T.1 murine mammary tumor cells was able to induce tumor growth by inhibiting IL-2 mediated activation of NK cells." (PMID 31555295, 2019). "We first evaluated secretion of IL-2 from transfected tumor cells in vitro." (PMID 31061426, 2019). "Moreover, it has also been shown to enhance the activity of NK cells and CTL, promote IL-2 secretion by spleen cells of mice, and increase the serum levels of IgG, IgG2a, and IgG2b antibodies in tumor-bearing mice." (PMID 31334112, 2019). "It was found that conditioned medium from SDCSC exosome-trained neutrophils suppressed the proliferation of activated T cells and attenuated the expression of Il2, a key cytokine for T cell proliferation, and Ifnr, a mediator of T cell-dependent anti-tumor responses, in activated T cells." (PMID 30683126, 2019). "Indeed, recent case study of the patient with inoperable NSCLC (CT4, cN3, cM0, stage IIIb) treated with autologous ex vivo activated (TKD/IL-2) NK cells with anti-PD-1 antibody as a second-line therapy demonstrated a long-term tumor control." (PMID 31652993, 2019). "Further, the role of IL-2 in enhancing the population of tumor-reactive T cells was also reported." (PMID 31137873, 2019). "On the basis of these results, we investigated if an additional supply of IL-2 might be helpful for tumor control." (PMID 31462678, 2019). "Additionally, a prolonged overall survival rate was demonstrated in tumor-bearing mice treated by co-delivery of IL-2 and PCT." (PMID 30875934, 2019). "Furthermore, blocking NO production in mice via genetic deletion of NOS2 (inducible NOS [iNOS]) inactivation function abolished NK cell responses that confirming the main positive role of NO to support IL-2-NK cells induction against tumor cells." (PMID 31457012, 2019). "Immunotherapy using a monoclonal antibody against the tumor-associated disialoganglioside GD2, granulocyte macrophage colony-stimulating factor (GM-CSF), and IL-2 was associated with a significantly improved outcome as compared with standard treatment in patients with neuroblastoma." (PMID 30693030, 2019). "Afterwards, the expression levels of 12 cytokines including IL-1a, IL-1b, IL-2, IL-4, IL-6, IL-8, IL-10, IL-12, IL-17A, TNFα, IFNγ and GM-CSF in secretome of hWJ-MSCs alone as well as in supernatant of tumor cells before and after treatment with hWJ-MSCs secretome were evaluated." (PMID 31857970, 2019). "However, the effect of a tumor cell to T cell ratio on INF-γ secretion was less significant than IL-2." (PMID 30699956, 2019). "Blocking IL-2 and IL-15 activities in the context of IL-1β administration completely abrogated the ability of Pmel-1 cells to control tumor growth and shortened the life span of tumor-bearing mice, suggesting a strong dependence of IL-1β enhancement of T cell antitumor function on IL-2 and IL-15." (PMID 31405895, 2019). "The ability of HDC to shield tumor-reactive lymphocytes represents a vital basis for clinical trials testing the combination of HDC (as an indirect antioxidant) with (T/NK cell-stimulating) low-dose interleukin-2 (IL-2)." (PMID 31781489, 2019). "IL-2 treatment can activate T cells in not only tumor tissues but also other tissues and the DLNs." (PMID 31462678, 2019). "Moreover, the inhibition of NO production led to block IL-2 roles to induce NK cytotoxicity against tumor cell." (PMID 31457012, 2019). "IL-2 ability to reverse NK cell anergy was also shown in vivo in RMA-S tumor bearing mice." (PMID 31547251, 2019). "Additionally, a low number of preclinical data were also present prior to 2008 and demonstrated that IL-2 and IL-12 have potent antitumor and antimetastatic activities in several murine tumor models through an immune-mediated, T-cell-dependent mechanism." (PMID 31847214, 2019). "Ex vivo, patient tumor samples are treated with high dose IL-2 to preferentially expand TIL." (PMID 30842774, 2019).
tumor (continued). "Indeed, significantly higher levels of IL-2 and IL-2R were expressed in tumor-derived CD8+ T cells than in matched peripheral blood CD8+ T cells." (PMID 31623665, 2019). "When stimulated by IL-2, they become activated against tumor cells." (PMID 31632199, 2019). "In terms that NKYS cell line is dependent on IL‐2, We hypnosis that the tumour need IL‐2 to grow." (PMID 30484952, 2019). "NK cells also had anti-tumor responses and were reprogrammed to act on specific cellular pathways when stimulated with different cytokine priming programs, IL-12 and IL-15, or IL-15, or IL-2, in the presence of adenosine." (PMID 31396523, 2019). "Therefore, anti-tumor effector IL-2 deprivation by Treg in the TME promotes tumor tolerance through limitation of effector T cell responses." (PMID 31681327, 2019). "An example of anti-tumor cytokine therapy involves interleukin 2 (IL-2)." (PMID 31847387, 2019). "This is in marked contrast to stimulation by a single agent, which achieved the greatest increases in IFN-γ, TNF-α, and IL-2 secretion as well as the greatest increase in T-lymphocyte proliferation and the greatest enhancement of tumor cell lytic activity in vitro." (PMID 31694582, 2019). "Taken together, these data support a model whereby NK cell-tumour interactions facilitated the upregulation of CD25 expression allowing NK cells to respond to T cell-derived IL2, which induced metabolic signalling pathways, cellular growth and robust NK cell effector function." (PMID 31595191, 2019). "Furthermore, the induced NO (iNOS) by NK cells when cultured with tumor cells in the presence of recombinant IL-2 that in turn induced IFNγ production that in turn enhance the cytotoxic effects of NK cells." (PMID 31457012, 2019). "Based on the discovery of the potent anti-tumour activities of several pro-inflammatory cytokines in animal models, clinical research led to the approval of recombinant interferon-alpha and interleukin-2 for the treatment of several malignancies, even if efficacy was only modest." (PMID 30413827, 2019). "We first treated a B16F10 tumor with an FDA-approved free IL-2." (PMID 31462678, 2019). "Finally, STAT5ca-expression in tumor-specific T cells had better therapeutic potential than the potentiation of standard CD8 T effector cells with combined infusions of IL-2 complexes, the effect of which disappeared at the end of treatment." (PMID 31766350, 2019). "These include direct effects on tumor cells by cytokines produced by CD4+ T cells such as IFN-γ, TNF-α, and IL-2, modulation of DCs and other antigen presenting cells in the tumor microenvironment as well as direct killing of tumor cells by cytolytic CD4+ cells." (PMID 31379821, 2019). "Moreover, when conjugated to tMUC1 antibody, IL-2 stimulated the proliferation of activated human lymphocytes in vitro and triggered resting NK cells to lyse tumor cells." (PMID 31114758, 2019). "Interestingly, the culture of E.G7 cancer cells in the RCCS for 72 h resulted in an apparent disruption of tumor evasion function as JAWS II DC were able to promote IL-2 production by the CD4+ T cells." (PMID 31602007, 2019). "As well as T-cell checkpoint blockage, hypoxia and glucose depletion result in lactic acid accumulation, consequently leading to low pH values in the tumor microenvironment, which suppresses the function of effector T cells, characterized by reduced IL-2 and IFN-γ secretion and lytic activity." (PMID 31824840, 2019). "In the tumor microenvironment, cytokine (e.g., IL-2, IL-12, and IL-15) activation could antagonize the effects of immunosuppressive factors and improve CAR-T cell efficacy." (PMID 31754328, 2019). "This was affected by the initial tumor size, number of cells and concentration of IL-2." (PMID 30871264, 2019). "Therefore, histamine in combination with IL-2, an NK cell-activating cytokine, has shown promising results in the activation of anti-tumor immune responses." (PMID 31167464, 2019).
tumor (continued). "The B16 tumor is sensitive to NK cells and CTLs34,35, both of which can be activated by IL-2." (PMID 31462678, 2019). "Even in vitro, replicon expression in B16F10 tumor cells transfected with WT replicon ABC encoding IL-2 decayed to near baseline by 48 hr, while secreted IL-2 protein was detected over at least 3 days in culture from the mutant replicons and at much higher levels than the WT construct." (PMID 31061426, 2019). "On the flipside, the deficit in IL-2 production might lead to poor proliferation and a compromised long-term persistence of tumor-specific CAR T cells." (PMID 31195686, 2019). "IL-2 was one of the earliest cytokines tested for improving anti-tumor immunity." (PMID 31456796, 2019). "Importantly, our data show that, for high dose IL-2-activated NK cells, all subsets can get activated by tumor cells in the context of laboratory setting mimicking tumor microenvironment." (PMID 29988376, 2018). "Having observed differences in NK cell-mediated cytotoxic responses following tumor priming and IL-2 stimulation, we next wanted to determine whether these two approaches differentially regulate the expression of NK cell activating receptors." (PMID 30761160, 2018). "We could demonstrate that the cultured UCB γδ T cells were based on gene expression and efficient cytokine producers, especially with regard to IL-1β, IL-2, IL-8, and IL-15, and had a capacity for killing tumor cells comparable to cultured PB γδ T cells." (PMID 29707004, 2018). "When CNI-1493 was administered in conjunction with continuous IL-2 to animals with preexisting tumors, a 10-fold higher dose of IL-2 could be infused, and all animals had a tumor response." (PMID 30057605, 2018). "These IL2 fusion proteins are aimed to accumulate tissue-specifically in the tumor, resulting in an increased cytokine concentration inside the tumor and thus better anti-tumor activity." (PMID 29467958, 2018). "CAR33VH and My96CAR elaborated high levels of IFNγ, TNFα, and IL-2 in response to CD33high tumor lines MOLM-14 and HL-60, whereas CAR T-secreted cytokines were not significantly induced when challenged with CD33moderate line KG-1a, or CAR T cells incubated alone, demonstrating antigen specificity." (PMID 30524966, 2018). "We, therefore, hypothesised that secreted IL-2 produced by vvDD-IL-2 treatment might be more toxic for mice with a heavy tumour burden, due to more viral replication leading to increased IL-2 expression, and a weakened clinical state." (PMID 30410056, 2018). "This corresponds to a greater induction of IFN-gamma, TNF-alpha and IL-2 in response to MOLM-14 as compared to HL-60 tumor cells, and a greater induction in response to HL-60 vs. KG-1a, and also correlates with the relative cytotoxic activity of the anti-CD33 CARs against these cell lines." (PMID 30524966, 2018). "IL-2-cultured Iqgap1−/− NK cells were also able to kill various tumor cells in vitro." (PMID 29892299, 2018). "Additionally, reduced CD25, CD73, and CTLA-4 on tumor-infiltrating CD4+ T cells in both age groups suggest reduced Treg-mediated suppression within IL-2/CD40-treated tumors." (PMID 30560130, 2018). "One may speculate that the observed anti-tumor effects of N-BPs or high-dose IL-2 monotherapy as well as allogenic stem cell transplantation are influenced by γδ T-cells without being recognized as such." (PMID 29725332, 2018). "In addition, silencing PD-L1 or PD-L2 specifically on DCs enhanced proliferation of tumor-specific CTLs and CD4+ T-cells, augmented production of IFN-γ, tumor-necrosis factor alpha (TNFα), IL-2, IL-5, and IL-12 and promoted cytolysis of tumor cells in vitro." (PMID 30568653, 2018).